CERCAM (cerebral endothelial cell adhesion molecule)
Description:
Probable cell adhesion protein involved in leukocyte transmigration across the blood-brain barrier. Does not express any beta-galactosyltransferase activity in vitro.
Synonyms: CEECAM1; GLT25D3
Tractability: Antibody: UniProt predicts a signal peptide or a membrane-spanning region. PROTAC: ubiquitination databases record sites on it.
Gene: Protein-coding gene on chromosome 9 (128,411,751 to 128,437,351, forward strand). Ensembl gene ENSG00000167123.
Subcellular location: Endoplasmic reticulum lumen
Subcellular location (Human Protein Atlas): Nucleoli; Nucleoplasm; Cell Junctions
Gene Ontology:
Molecular function: identical protein binding; protein binding; procollagen galactosyltransferase activity
Biological process: cell adhesion; leukocyte cell-cell adhesion
Cellular component: plasma membrane; endoplasmic reticulum lumen
Genetic constraint (gnomAD): Loss-of-function variants: 59 observed, 63.22 expected, observed/expected ratio (o/e) 0.93, 90% interval 0.76 to 1.16. The upper end of that interval is the gene's LOEUF score, 1.16, which puts it in group 5 of 6, group 1 being the genes least tolerant of losing a copy. Missense variants: 827 observed, 799.71 expected, observed/expected ratio (o/e) 1.03, 90% interval 0.98 to 1.1. Synonymous variants: 313 observed, 324.17 expected, observed/expected ratio (o/e) 0.97, 90% interval 0.88 to 1.06.
Homologues: Orthologues: chimpanzee CERCAM (99% identical), macaque CERCAM (96% identical), pig CERCAM (92% identical), dog CERCAM (88% identical), guinea pig CERCAM (85% identical), rat Cercam (85% identical), mouse Cercam (83% identical), tropical clawed frog cercam (59% identical), zebrafish cercam (58% identical), Drosophila melanogaster CG31915 (40% identical), Caenorhabditis elegans D2045.9 (29% identical). Paralogues in human: COLGALT1 (56% identical), COLGALT2 (52% identical), PLOD3 (21% identical), PLOD1 (21% identical), PLOD2 (20% identical).
Diseases named in the same sentence as CERCAM in open-access papers:
CERCAM is named in the same sentence as 14 diseases in open-access papers, as found by Europe PMC text mining. Sharing a sentence is not in itself a finding about the gene and the disease. The quoted sentences say what the papers report.
bladder cancer (6 papers, 2021 to 2024). "CERCAM, an adhesion molecule, is associated with poor prognosis in bladder cancer and enhances tumor cell proliferation and invasion." (PMID 38341586, 2024). "Through the use of bioinformatics analysis, CERCAM was found to have exhibited a significant association with bladder cancer patients' RFS and OS." (PMID 34105305, 2021). "Consistently, CERCAM silencing suppressed tumor growth in the subcutaneous implant tumor model in vivo, further indicating the underlying effect of CERCAM on bladder cancer." (PMID 34105305, 2021). "Compared with normal cells, CERCAM was upregulated in bladder cancer, and CERCAM overexpression significantly promoted bladder cancer cell viability, DNA synthesis and cell invasion, while CERCAM silencing was inhibitory." (PMID 39655212, 2024). "It partially neutered the promotive roles of CERCAM overexpression in the ability of bladder cancer cells to proliferate and to invade." (PMID 34105305, 2021). "In contrast, CERCAM silencing suppressed bladder cancer cell viability, DNA synthesis, and cell invasion." (PMID 34105305, 2021). "In vitro, CERCAM overexpression not only significantly promotes bladder cancer cell viability, DNA synthesis, and cell invasion, but also alters E‐cadherin and N‐cadherin expression pattern; in vivo, CERCAM silencing suppressed tumor growth in nude mice." (PMID 34105305, 2021). "Then, T24 and 5637 cells were infected with lv‐NC/lv‐CERCAM or lv‐sh‐NC/lv‐sh1‐CERCAM/lv‐sh2‐CERCAM and assessed for bladder cancer cell viability and DNA synthesis ability." (PMID 34105305, 2021). "CERCAM‐mediated alteration in AKT phosphorylation suggests the potential involvement of the PI3K/AKT signaling in CERCAM functions in bladder cancer." (PMID 34105305, 2021). "In vitro, functional experiments such as MTT, EdU, and Transwell assays showed that CERCAM overexpression markedly enhanced bladder cancer cell viability, DNA synthesis, and cell invasion." (PMID 34105305, 2021). "The PI3K inhibitor LY294002 treatment exerted similar effects as did CERCAM on silencing bladder cancer cell behaviors." (PMID 34105305, 2021). "The PI3K inhibitor LY294002 treatment manifested similar effects as CERCAM silencing on bladder cancer cell behaviors and partially impaired the promotive functions of CERCAM overexpression upon the capacity of bladder cancer cells to proliferate and invade." (PMID 34105305, 2021). "The PCR‐based analysis revealed an aberrant upregulation of CERCAM in bladder carcinoma tissues and cells when compared with normal controls." (PMID 34105305, 2021). "Considering its effect on the modulation of cell growth, survival, and metastasis, the involvement of the PI3K/AKT signaling in CERCAM functions on bladder carcinoma cell proliferation was then investigated." (PMID 34105305, 2021). "The PI3K/AKT signaling is suspected of interfering participate in the functions of CERCAM in bladder carcinoma." (PMID 34105305, 2021). "These alterations in Vimentin, Twist, N‐cadherin, and E‐cadherin levels further proved and explained the promotive roles of CERCAM overexpression in the ability of bladder carcinoma cells to proliferate and to invade." (PMID 34105305, 2021). "Results of the experimental analysis show an abnormal upregulation of CERCAM in tissues and cells of bladder carcinoma." (PMID 34105305, 2021). "In vitro, CERCAM overexpression markedly enhanced the viability, DNA synthesizing capacity, and invasive ability of bladder carcinoma cells." (PMID 34105305, 2021). "We constructed a prognostic model based on Necroptosis subtype-related prognosis DEGS by lasso algorithm and multivariate COX analysis, which consists of 6 predictors (CERCAM POLR1H, KCNJ15, GSDMB, EHBP1, TRIM38), among which CERCAM is closely related to bladder cancer." (PMID 35478725, 2022). "Furthermore, CERCAM overexpression or silencing was conceived in bladder cancer cells, and the effects of CERCAM on the behaviors of bladder cancer cells were analyzed." (PMID 34105305, 2021).
bladder cancer (continued). "The PI3K/AKT signaling is suspected of participating in the functions of CERCAM in bladder cancer." (PMID 34105305, 2021). "Notably, CERCAM overexpression remarkably increased N‐cadherin levels but decreased E‐cadherin levels in bladder cancer cells." (PMID 34105305, 2021). "In bladder cancer cell lines, CERCAM was also upregulated compared with that in normal cells." (PMID 34105305, 2021). "Finally, CERCAM‐overexpressing bladder cancer cells were treated or non‐treated with the PI3K inhibitor LY294002." (PMID 34105305, 2021). "In conclusion, cell adhesion molecule CERCAM is overexpressed in bladder cancer tissues." (PMID 34105305, 2021). "According to GSE31684, CERCAM was remarkably associated with the RFS (hazard ratio = 0.293, p = 0.00026) and the OS (hazard ratio = 0.337, p = 0.0012), respectively, in patients ailing from bladder cancer." (PMID 34105305, 2021). "When taken together, the cell adhesion molecule CERCAM is overexpressed in bladder cancer tissues." (PMID 34105305, 2021). "In vitro, CERCAM overexpression significantly promoted bladder‐cancer cell viability, DNA synthesis, and cell invasion, whereas CERCAM silencing suppressedthe viability of bladder cancer cell, DNA synthesis, and cell invasion compared with that in the lv‐NC or lv‐sh‐NC group." (PMID 34105305, 2021). "For instance, it has been shown that CERCAM is overexpressed in bladder cancer tissues and provided evidence in vitro that CERCAM promotes bladder cancer cell viability, DNA synthesis, and cell invasion, suggesting that CERCAM may function as an oncogene in bladder cancer." (PMID 37803318, 2023). "The PI3K/AKT signaling might participate in the functions of CERCAM in bladder cancer." (PMID 34105305, 2021). "More importantly, in CERCAM‐overexpressing bladder cancer cells, LY294002 treatment partially abated the promotive roles of CERCAM overexpression in the malignant behaviors of bladder carcinoma cells." (PMID 34105305, 2021). "The dynamic effects of CERCAM overexpression and LY294002 upon bladder carcinoma cell proliferation and invasion were examined." (PMID 34105305, 2021). "By using a CoxPH multifactor analysis, CERCAM was closely related to recurrence‐free survival (RFS; hazard ratio = 0.451, p = 0.032) and the overall survival (OS; hazard ratio = 0.281, p = 0.00013) in patients with bladder cancer." (PMID 34105305, 2021). "In collected clinical tissue samples, the expression of CERCAM was shown to be increased within bladder carcinoma tissues rather than in non‐cancerous tissue controls." (PMID 34105305, 2021).
breast carcinoma (2 papers, 2024). "Initially, univariate Cox regression analysis revealed that 12 genes were associated with the prognosis of breast cancer, followed by LASSO analysis to derive a prognostic signature composed of 8 genes, including CERCAM, EMP1, SDC1, PRKG1, XG, TNN, WLS, and PDLIM4." (PMID 38728370, 2024). "In HNSCC, CERCAM promotes malignant biological behavior of tumor and M2 polarized immune infiltration of macrophages, which are independent risk factors for predicting OS in patients.However, CERCAM has not been shown to be an independent prognostic risk factor in breast cancer." (PMID 39418248, 2024).
colorectal cancer (2 papers, 2020 to 2021). A primary or metastatic malignant neoplasm that affects the colon or rectum. "Based on an analysis of the upregulated genes in the TME that were evaluated through a Kaplan–Meier survival analysis using colorectal cancer data from TCGA, CERCAM was found to be associated with a poor survival and epithelial to mesenchymal transition (EMT)." (PMID 34062897, 2021). "Similarly, colorectal cancer patients with high expression of CRIP2, PRAM1, HSPB2 or CERCAM had poorer OS comparing with low expressed groups (logrank = 0.0073, 0.0053, 0.0036 and 0.0023, respectively)." (PMID 33125346, 2020).
ovarian carcinoma (2 papers, 2020 to 2021). A malignant neoplasm originating from the surface ovarian epithelium. "CERCAM is known as an unfavorable prognostic marker in urothelial, renal, and ovarian cancers implying the importance of the variants in these genes." (PMID 32211398, 2020). "CERCAM (cerebral endothelial cell adhesion molecule) has a low cancer specificity, has been detected in all cancer tissues and is known as an unfavorable prognostic marker in renal cancer, urothelial cancer and ovarian cancer." (PMID 34062897, 2021).
Colon Cancer (1 paper, 2023). "Although it has been found that the expression level of CERCAM in Colon Cancer and kidney cancer affects the prognostic level of tumors." (PMID 37803318, 2023).
head and neck squamous cell carcinoma (1 paper, 2023). A squamous cell carcinoma that arises from any of the following anatomic sites: lip and oral cavity, nasal cavity, paranasal sinuses, pharynx, larynx, and salivary glands. "This study aimed to investigate the relevance of cerebral endothelial cell adhesion molecule (CERCAM) expression to head and neck squamous cell carcinoma (HNSCC) prognosis and immune infiltration by macrophage M2 polarization." (PMID 37803318, 2023).
oesophageal cancer (1 paper, 2023). "The top GPR176-correlated genes (PDPH, KIREL1, CLEC12A-AS1, CERCAM, IKBIP, LOX, COL5A2 and ELF3) were more highly expressed in oesophageal cancer than in normal tissue (p < 0.05), but the converse was true for C9orf152 and MT-TP (p < 0.05)." (PMID 37584712, 2023).
rectal cancer (1 paper, 2021). A primary or metastatic malignant neoplasm that affects the rectum. "Very few studies on the function and mechanism of CERCAM in colon and rectal cancers have been published." (PMID 34062897, 2021).
tumor (11 papers, 2021 to 2024). "CERCAM, as a gene associated with cell adhesion as well as extracellular matrix remodeling, its role in tumors is mainly to promote tumor epithelial cell migration and promote cancer progression." (PMID 37803318, 2023). "Taken together, these results suggest that CERCAM expression may be associated with increased tumor malignancy and poorer prognosis in HNSCC." (PMID 37803318, 2023). "In summation, the molecules ZNF165, MXRA7, CEMIP, ARL4C, and CERCAM collectively represent prospective therapeutic nexus points in impeding tumor advancement." (PMID 39624211, 2024). "CERCAM promotes tumor malignant biological behavior and promotes macrophage M2 polarization immune infiltration in HNSCC." (PMID 37803318, 2023). "We also examined the difference in mRNA expression of CERCAM in normal and tumor tissues through the TCGA database, while the results of IHC using the HPA database further confirmed the overexpression of CERCAM in tumor tissues." (PMID 37803318, 2023). "To re‐iterate the tumor‐promotive effects of CERCAM overexpression, CERCAM was overexpressed in a non‐cancerous cell line, SV‐HUC‐1." (PMID 34105305, 2021). "On day 28 of the injection, the mice were anesthetized and killed; in vivo CERCAM silencing significantly decreased the tumor weight." (PMID 34105305, 2021). "A subcutaneous implant model was conducted in nude mice, and the in vivo effects of CERCAM silencing on tumor growth were examined and recorded." (PMID 34105305, 2021). "CERCAM, also known as cerebral endothelial cell adhesion molecule, is a cell adhesion molecule, and studies have shown that CAFs enhance epidermal cell adhesion and promote tumor cell metastasis." (PMID 39418248, 2024). "In addition, we constructed a column line graph model including tumor clinical N stage and CERCAM expression level as factors." (PMID 37803318, 2023). "We then analyzed the role of CERCAM in head and neck squamous carcinoma by single cell level and immune cell infiltration level, and we found that CERCAM was expressed on cells including tumor cells and correlated with the infiltration of M2 macrophages in the tumor microenvironment." (PMID 37803318, 2023). "We first used the UALCAN platform to analyze the DNA methylation levels of CERCAM genes in patient tumor tissues with their matched normal tissues in the TCGA-HNSCC dataset, we found that the CERCAM gene showed lower methylation levels in tumor tissues, with a significant difference (P < 0.05)." (PMID 37803318, 2023). "In addition, CERCAM promotes tumor cell adhesion in head and neck squamous carcinoma and promotes tumor progression through several oncogenic signaling pathways." (PMID 37803318, 2023). "It was found that CERCAM was most expressed in fibroblasts, plasma cells, and tumor cells, followed by expression in myofibroblasts, monocytes/macrophages, endothelial cells, and mast cells, while no or no significant expression in CD4convT cells, CD8T cells, CD8Tex, and Myocyte." (PMID 37803318, 2023). "More importantly, in the T24 and 5637 cells that were co‐transduced with Lv‐sh‐CERCAM and lv‐CERCAM, the tumor‐suppressive effects of CERCAM knockdown on cell viability, DNA synthesis, cell invasion, and related markers were partially impaired by CERCAM overexpression." (PMID 34105305, 2021). "HEYL, SLC2A3, and FBN1 were found to mediate tumor progression and chemoresistance mainly by facilitating angiogenesis and EMT, while CERCAM, ANXA1, and SPOCD1 promoted tumor progression through the PI3K/AKT and EGFR signaling pathways." (PMID 39033778, 2024). "For example, BCL9L, P2RX6, RER1, EFNA2, CASK, CERCAM, and PTPRN were demonstrated to promote EMT, metastasis, and invasion of tumor cells." (PMID 35586092, 2022). "Cox regression analyses were performed to identify independent clinical prognostic parameters to construct a combined nomogram which includes the expression of CERCAM, MIA2, HS6ST2, ONECUT2, SOX12, TMEM132A, pT stage, tumor size and ISUP grade." (PMID 35954418, 2022).
tumor (continued). "In order to evaluate the expression of CERCAM better, we used two head and neck squamous carcinoma datasets (GSE25099, GSE139869) from the GEO database and found that CERCAM was also highly expressed in tumor tissues." (PMID 37803318, 2023). "Also, in vivo CERCAM silencing decreased the protein levels of PCNA and CERCAM in tumor tissues compared with those in the lv‐sh‐NC group." (PMID 34105305, 2021). "Therefore, we verified the effect of CERCAM on the malignant biology of tumor cells by inhibiting its expression in HNSCC cells in vitro, and the results showed that the downregulation of CERCAM inhibited the viability of HNSCC cells, which was consistent with the previous results." (PMID 37803318, 2023).
cancer (10 papers, 2021 to 2024). A tumor composed of atypical neoplastic, often pleomorphic cells that invade other tissues. "Our findings revealed that CERCAM was predominantly expressed in inflammatory cancer-associated fibroblasts (iCAFs), a type of cancer-associated fibroblasts known for their strong pro-proliferation properties." (PMID 38341586, 2024). "We next analyzed the co-expressed genes with CERCAM in HNSCC to further explore the mechanisms associated with its involvement in cancer." (PMID 37803318, 2023). "In a parallel vein, CERCAM's dysregulated expression profiles in diverse cancers hint at its contributory role in oncogenesis and malignant transformation." (PMID 39624211, 2024). "Ascore comprises four genes (CERCAM, EMP1, GNLY, and PTPRR), which have been previously reported to be strongly associated with cancer." (PMID 38341586, 2024). "We firstly analyzed the differences in the expression levels of CERCAM in various human cancers from the Timer2.0 database and found that CERCAM expression was increased in many tumors, including HNSCC." (PMID 37803318, 2023). "The presented study found that the expression of CERCAM was higher in fibroblasts than in cancer cells, so further studies are needed to investigate its role in TME." (PMID 37069207, 2023). "Taken together, the results of gene enrichment analysis suggest that high expression of CERCAM may be involved in functional signaling pathways related to cell adhesion in HNSCC to promote cancer development." (PMID 37803318, 2023). "However, the role of CERCAM in influencing macrophage M2 polarization for cancer progression in HNSCC is still unclear." (PMID 37803318, 2023). "Besides, CERCAM expression increased with the progression of the American Joint Committee on Cancer staging (AJCC staging, namely pathological stage) and TNM staging." (PMID 34105305, 2021). "CERCAM is upregulated in a variety of malignant cells and in TME, and has been defined in some cancers as a prognostic marker." (PMID 39418248, 2024). "High expression of CERCAM, HS6ST2, ONECUT2, SOX12 and TMEM132A and low expression of MIA2 related to poor outcomes for progression-free survival and cancer-specific survival." (PMID 35954418, 2022). "Cerebral endothelial cell adhesion molecule (CERCAM), a member of cell adhesion molecules, was originally identified in the blood–brain barrier, and many studies have shown that CERCAM is aberrantly expressed in many cancers and is also involved in cancer development and malignant progression." (PMID 37803318, 2023).
CERCAM also shares sentences with these, for which no sentence is quoted: kidney cancer (1 paper); neurological diseases (1); renal carcinoma (1); triple-negative breast carcinoma (1).